GPX4 (glutathione peroxidase 4)
Diseases named in the same sentence as GPX4 in open-access papers (continued):
Sharing a sentence is not in itself a finding about the gene and the disease.
breast carcinoma (continued). "The high ACSL4/low GPX4 profile holds significant practical value in predicting pathological complete response to neoadjuvant chemotherapy in breast cancer.A strategy to enhance chemosensitivity through the induction of ferroptosis has been identified." (PMID 39867656, 2024). "designed a novel nanoparticle comprising ferritin, erastin, and rapamycin, which induces ferroptosis by modulating GPX4 activity and demonstrates anti-breast cancer effects in a mouse model." (PMID 39759144, 2024). "GPX4, a pivotal player conferring treatment resistance, heavily relies on breast cancer cells in a mesenchymal state." (PMID 38140764, 2024). "ORes inhibits breast cancer cell growth by inducing ferroptosis through suppression of the EGFR/PI3K/AKT/GPX4 signalling axis." (PMID 39881871, 2024). "In summary, ORes induces ferroptosis in breast cancer cells through inactivation of GPX4, accumulation of ROS, increased iron levels, and enhanced lipid peroxidation." (PMID 39881871, 2024). "Another study found that ketamine-induced ferroptosis by reducing the expression of Gpx4, which is involved in glutathione metabolism by catalyzing the reduction of peroxides in breast cancer cells." (PMID 39459017, 2024). "In our study, we observed a significant decrease in GPX4 protein levels in ORes-treated breast cancer cells and tissues compared to that in controls, suggesting that ORes-induced ferroptosis is mediated by the inhibition of GPX4." (PMID 39881871, 2024). "Silencing glycogen synthase kinase-3β (GSK-3β) with low expression in breast cancer can upregulate nuclear factor erythroid 2-related factor 2 (Nrf2) and GPX4 expression, inhibit tumor cell ferroptosis, and promote progression." (PMID 39664391, 2024). "Subsequent experiments confirmed that ORes induced ferroptosis by inhibiting GPX4 activity and increasing ROS, ferrous ions, and lipid peroxidation levels in breast cancer cells, thereby inhibiting their growth both in vivo and in vitro." (PMID 39881871, 2024). "MiR-324-3p was upregulated by metformin in breast cancer cell lines and downregulated GPX4 to induce ferroptosis." (PMID 38392340, 2024). "AM resulted in remarkable mitochondrial shrinkage, enhanced Fe2+ and ROS levels, and significantly decreased mRNA and protein expression of SLC7A11 and GPX4 in breast cancer cells, indicating that AM suppressed cell growth and invasion via ferroptosis." (PMID 39021832, 2024). "As reported, a high ACSL4/low GPX4 profile holds significant practical value in predicting pathological complete response to neoadjuvant chemotherapy in patients with breast cancer." (PMID 39867656, 2024). "Collectively, these findings suggest that ORes induces ferroptosis in breast cancer cells by inhibiting the EGFR/PI3K/AKT/GPX4 signalling axis." (PMID 39881871, 2024). "METTL16 epigenetically enhances GPX4 expression through m6A modification and promotes breast cancer progression by inhibiting ferroptosis." (PMID 38550378, 2024). "Clinical studies have found that the active ingredient dihydrotanshinone I in Salvia miltiorrhiza can inhibit GPX4 expression in breast cancer cells, promote ferroptosis, and inhibit tumor growth in mice without significant side effects." (PMID 39664391, 2024). "Inhibiting the activity of the System Xc-/GSH/GPX4 axis is an effective way to prevent breast cancer growth and treat breast cancer." (PMID 39664391, 2024). "Moreover, some related studies have identified impaired expression of the GPX4 gene in PBMCs from breast cancer patients which could serve as a biomarker indicating an increased risk for breast cancer, indicating that the expression of GPX4 in PBMCs is indeed related to some particular disease." (PMID 38515187, 2024). "GPX4 inhibition-mediated ferroptosis is essential for the radiosensitivity of breast cancer and hepatocellular carcinoma." (PMID 38228715, 2024).
breast carcinoma (continued). "While this study demonstrated that ORes exerted anti-breast cancer activity by inducing ferroptosis through the inhibition of the EGFR/PI3K/AKT/GPX4 signalling axis, it is important to note some limitations." (PMID 39881871, 2024). "Inhibiting α-tocopherol succinate synthesis provides a novel direction for the treatment of breast cancer resistant to GPX4 inhibitors." (PMID 39664391, 2024). "Tissue sections from breast carcinoma showed distinct populations of CD8+GPX4+, CD8+GCLC+, CD8+GPX4+GCLC+, and CD8+Ki67+GPX4+GCLC+ cells." (PMID 38441967, 2024). "In the present study, we determined that EGFR knockdown in breast cancer cells inhibited GPX4 expression." (PMID 39881871, 2024). "Ketamine, an inhibitor of lysine acetyltransferase 5 (KAT5), inhibits GPX4 by decreasing the levels of H3K27ac, leading to the execution of ferroptosis in breast cancer." (PMID 38392340, 2024). "T7‐MNTs showed the targeting ability to the lysosomes in the breast cancer cells, which offer a physical and biological platform to collaboratively achieve GPX4 inhibition and ferroptosis induction in vivo." (PMID 38095513, 2024). "Here, our data suggest that PRODH decreases GPX4 expression and enhances ferroptosis in breast cancer cells." (PMID 39457440, 2024). "In this study, we uncovered that ORes induces ferroptosis in breast cancer cells through the inhibition of the EGFR/PI3K/AKT/GPX4 signalling axis." (PMID 39881871, 2024). "To further validate the regulation of the EGFR/PI3K/AKT/GPX4 signalling axis by ORes in breast cancer cells, we performed Western blot analysis to assess the expression levels of key proteins in this pathway." (PMID 39881871, 2024). "Generally, GPX4 expression is upregulated in breast cancer, closely related to the increased expression of the two subunits of the cysteine/glutamate antiporter (xCT), SLC7A11 and SLC3A2." (PMID 39664391, 2024). "Inhibition of lysine acetyltransferase 5 (KAT5), which reduces H3K27ac abundance at the GPX4 promoter, downregulates GPX4 and promotes ferroptosis in breast cancer cells." (PMID 39568772, 2024). "Its derivative DMOCPTL induces ferroptosis and early growth response-mediated apoptosis in breast cancer cells through the ubiquitination of GPX4." (PMID 38292937, 2024). "Dihydroisotanshinone I, obtained from Danshen, Salvia miltiorrhiza Bunge (Lamiaceae), triggers ferroptosis by inhibiting GPX4 expression in breast cancer." (PMID 38292937, 2024). "Dihydroisotanshinone I induces ferroptosis in Breast cancer cells by inhibiting GPX4, leading to depletion of intracellular glutathione and a sharp increase in GSSG." (PMID 38738174, 2024). "The study also found that AA increased iron and MDA levels in the tumor tissues and decreased GPX4 levels, indicating that it induces ferroptosis and has antitumor effects against breast cancer cells." (PMID 38633616, 2024). "Functionally, alloimperatorin directly decreases the expression levels of SLC7A11 and GPX4, thereby inhibiting the growth and invasion of breast cancer cells." (PMID 37488128, 2023). "In mice bearing tumors derived from mouse 4T1 breast cancer cells, the prodrug 42 (1 mg/kg, iv, 6× every other day) decreased Gpx4 and increased Egr1 protein levels and inhibited tumor growth." (PMID 36658724, 2023). "Enhanced GPX4 expression accelerates the proliferation and inhibits the ferroptosis of breast cancer cells." (PMID 37497000, 2023). "High expression level of GPX4 is correlated with bad prognosis in breast cancer (BC) patients, and the GPX4 reduction enhances the sensitivity of cancer cells to cisplatin." (PMID 37469703, 2023). "The downregulation of METTL16 decreased m6A methylation, suppressed the tumorigenic potential of breast cancer cells, induced ferroptosis, and enhanced the degradation of glutathione peroxidase 4 (GPX4) RNA in breast cancer cells." (PMID 36835633, 2023). "Inhibition of SCP2 was also found to increase cell viability in GPX4-/- fibroblasts or RSL3-treated breast cancer cells." (PMID 37422468, 2023).
breast carcinoma (continued). "Collectively, our data reveal that RUNX1-IT1 promotes breast cancer tumorigenesis through inhibiting ferroptosis via regulating IGF2BP1/GPX4 axis, providing a potential prognostic marker and therapeutic target for breast cancer." (PMID 37036576, 2023). "Previous studies have shown that chronic exposure to 27HC increases lipid accumulation in cells and enhances the resistance of breast cancer cells to ferroptosis, whereas GPX4 inhibition reverses this effect." (PMID 37891677, 2023). "It is worth mentioning that drug-resistant breast cancer cells often show stronger dependence on GPX4 and are more sensitive to GPX4 inhibitors." (PMID 37760042, 2023). "As we know, inhibition of SCP2 increases cell viability in GPX4-/- fibroblasts or RSL3-treated breast cancer cells, but the mechanism driving this remains obscure." (PMID 37422468, 2023). "As a result, the elevated GPX4 blocked lipid peroxidation and ferroptosis, thereby facilitating breast cancer tumorigenesis." (PMID 37036576, 2023). "SLC7A11 (xCT), SLC3A2 (xCT), and GPX4 expression have been reported to be elevated in a subset of TNBC breast cancer models predicting response to erastin (xCT inhibitor) and RSL3 (GPX4 inhibitor)." (PMID 37596261, 2023). "Metformin promotes ferroptosis via the up-regulation of miR-324-3p and down-regulation of GPX4 in breast cancer." (PMID 35805124, 2022). "For example, the high expression level of GPX4 is negatively correlated with the prognosis of breast cancer patients, but has good survival outcomes for pancreatic cancer patients." (PMID 34996454, 2022). "Sulfasalazine has been found to trigger breast cancer cell ferroptosis via the repression of GPX4 and SLC7A11 expressions and an increase in TFR1 and DMT1 expressions, particularly in cells with low estrogen receptor (ER) expression." (PMID 35805124, 2022). "It has been observed that the expression of GPX4 is higher in breast cancer tissues than in normal tissues, and that is adversely correlated with patients’ prognoses." (PMID 36355532, 2022). "Drug-resistant breast cancer cells are dependent on GPX4 and SLC7A11, which means they are vulnerable to ferroptosis caused by GPX4 and SLC7A11 inhibition." (PMID 36105219, 2022). "A polymer carbohydrates Lycium barbarum polysaccharide effectively prevents breast cancer cell proliferation and promotes ferroptosis via the System Xc−/GPX4 pathway." (PMID 36105219, 2022). "Curcumin induces ferroptosis in breast cancer cells by upregulating the expression of redox target genes such as HO-1 and downregulating antioxidants such as GPX4, an effect that is more pronounced than in normal human breast epithelial cells." (PMID 36505465, 2022). "Binding of FINS targeting GPX4 or SLC7A11 to RT can sensitize breast cancer cell lines or xenografts to radiation by enhancing ferroptosis sensitivity." (PMID 36467032, 2022). "The GPX4 which is driven by androgen receptor is a key factor of ferroptosis in LAR subtype breast cancer." (PMID 36467032, 2022). "Lycium barbarum polysaccharide (LBP), a traditional Chinese medicine, promotes ferroptosis in breast cancer by modulating the xCT/GPX4 pathway." (PMID 36467032, 2022). "MVA pathway and the activity of GPX4 is inhibited in ferroptotic death breast cancer cells induced by Simvastatin." (PMID 36505465, 2022). "Ketamine inhibits proliferation and promotes ferroptosis and apoptosis of breast cancer cells via targeting KAT5 KAT5/H3K27a/GPX4 axis." (PMID 35333774, 2022). "Studies have shown that FINs (such as RSL3, erastin, sorafenib, and sulfasalazine) can synergistically enhance RT efficacy by inhibiting SLC7A11 or inactivating GPX4 in models of glioma, lung cancer, fibrosarcoma, melanoma, breast cancer, and cervical cancer." (PMID 34996454, 2022).
breast carcinoma (continued). "Lidocaine induces the ferroptosis of ovarian and breast cancers by increasing miR-382-5p and decreasing SLC7A11, while ketamine induces ferroptosis by targeting the KAT5/GPX4 axis in breast cancer cells." (PMID 35805124, 2022). "Associated with mRNA and protein expression in cancer, 11,170 entries of mRNA expression from ICGC in seven cancer types were recorded for GPX4, which is highly expressed in breast cancer." (PMID 35805101, 2022). "Not only that, GPX4 activity was also observed to be significantly decreased in both breast cancer cells." (PMID 36242003, 2022). "Alloimperatorin, DT, Eup, FC, gallic acid, and LA can induce ferroptosis in breast cancer cells by decreasing the level of GPX4." (PMID 36355532, 2022). "GPX4 overexpression vectors significantly abolished the anti-invasive effect of alloimperatorin on breast cancer cells." (PMID 36355532, 2022). "The IHC assay showed that GPX4 protein was significantly increased in breast cancer tissue compared with normal breast tissue and related with breast cancer stages, which indicated the prominent role of GPX4 in breast cancer." (PMID 33472669, 2021). "Whereas the primary objective of this work was to understand how dyslipidemia impacts breast cancer pathology, we also identified a central role for GPX4, and resistance to ferroptosis, in metastasis." (PMID 34429409, 2021). "We find that GPX4 is strongly upregulated in a subset of breast cancer tissues compared to matched normal samples, and that this is tightly correlated with the increased expression of the xCT subunits SLC7A11 and SLC3A2." (PMID 33672555, 2021). "The drug-tolerant persister breast cancer cells acquire a dependency on GPX4, making cells sensitive to ferroptosis triggered by GPX4 inhibition." (PMID 34796174, 2021). "GPX4 played prominent role in breast cancer and was significantly increased in breast cancer tissue compared with normal breast tissue and related with breast stages." (PMID 33472669, 2021). "Sulfasalazine (SAS) can trigger ferroptosis in breast cancer cells by inactivating GPX4 and system Xc−, especially in cells with low ER expression." (PMID 34796174, 2021). "Paradoxically, the breast lines are at the same time hypersensitive to the Erastin and Rsl-3 indicating that breast cancer cells are addicted to the xCT/GPX4 axis to prevent ferroptosis." (PMID 33672555, 2021). "DT treatment significantly induces ferroptosis to suppress breast carcinoma through downregulating GPX4 protein expression in cell and xenograft models." (PMID 35118067, 2021). "Subsequent studies have identified GPX4 as a classical negative regulator of ferroptosis and have roles in various cancers such as clear-cell carcinomas (CCCs), breast cancer, colon cancer." (PMID 34820376, 2021). "The results revealed that GPX1, GPX2, GPX3 and GPX4 protein levels were markedly decreased in breast cancer when compared with normal controls." (PMID 32782436, 2020). "The ferroptotic agent (1S, 3R)-RSL3 and sulfasalazine (SAS) inactivate the peroxidase activity of GPX4 in breast cancer cells." (PMID 33292585, 2020). "Meanwhile, GPX4 regulates erastin-induced ferroptosis via the GSK3/NRF2/GPX4 signaling pathway in breast cancer." (PMID 33424539, 2020). "Metadherin (MTDH), which was overexpressed and predicted a poor prognosis in cancer, conferred a therapy-resistant mesenchymal-high state in breast cancer cells, but also increased sensitivity to ferroptosis by downregulating GPX4 and SLC3A2." (PMID 33292585, 2020). "The results of our current study suggest that curcumin triggers the molecular and cytological features of ferroptosis in breast cancer cells by upregulating HO-1 and downregulating GPX4." (PMID 33294119, 2020). "Using an MDA-MB-231 orthotopic breast cancer model, we found that the combination of the GPx4 inhibitor RSL3 and system xc− inhibitor sorafenib resulted in the strongest inhibition of tumor growth and lowest tumor weight." (PMID 31527591, 2019).
breast carcinoma (continued). "Low expression of GPX4 in breast-invasive ductal carcinoma correlated with high tumor grade and poor prognosis of breast cancer patients." (PMID 24790704, 2014). "Five SNPs, GPX3 rs2070593 (p=0.002), GPX4 rs2074451 (p=0.046), SELS rs9874 (p=0.029), TXNRD1 rs17202060 (p=0.007) and TXNRD2 rs7322262 (p=0.025), significantly interacted with DOBS to alter breast cancer risk." (PMID 24278290, 2013). "RUNX1 intronic transcript 1 binds to the N6-methyladenosine m6A reader IGF2BP1, promotes the formation of the IGF2BP1 biomolecular condensate, and improves the stability of GPX4 mRNA, which increases the expression of GPX4, blocks ferroptosis, and promotes breast cancer development." (PMID 40642070, 2025). "The cystine-glutamate antiporter xCT, which is involved in selenium uptake and cystine importation for glutathione synthesis and, thus, prevents ferroptosis by promoting GPX4 expression and activity, was found to be particularly crucial for breast cancer cells, contrarily to normal breast cells." (PMID 40227202, 2025). "In breast cancer, mucin 1-C binds to the CD44 variant to stabilize the SLC7A11 molecule, while H3K9me2/3 on the Mucin 1-C promoter suppresses its transcription, thereby affecting GPX4’s capacity to induce ferroptosis." (PMID 40327848, 2025). "Studies indicate that GPX3 may serve as a diagnostic biomarker for oxidative stress-induced encephalitis; furthermore, GPX4, another family member, regulates reactive oxygen species (ROS) levels in breast cancer cells to resist ferroptosis." (PMID 41170198, 2025). "Interestingly, GPX4 expression has shown an exceptional prognostic potential in breast cancer neoadjuvant therapy, and a high level of GPX4 is significantly correlated with metastasis-free survival." (PMID 39858015, 2025). "In breast cancer, RelB-mediated GPX4 upregulations drive tamoxifen resistance." (PMID 39935430, 2025). "Notably, artesunate has shown efficacy in breast cancer through glutathione peroxidase 4 (GPX4) inhibition, resulting in increased intracellular reactive oxygen species (ROS) and lipid peroxidation." (PMID 40758729, 2025). "Interestingly, we found a positive correlation between PNKP and GPX4 expression in all types of breast cancer including TNBC patients." (PMID 40743845, 2025). "Chloramine T has also been found to inhibit the cell growth of breast cancer and induce ferroptosis by targeting the GPX4 axis, indicating that it may become a potential new strategy for breast cancer treatment." (PMID 40009842, 2025). "Therefore, decreased cysteine, GSH, and GPX4 levels can lead to ferroptosis in breast cancer cells, thereby inhibiting tumor growth." (PMID 39664391, 2024). "Furthermore, Herceptin, also known as trastuzumab, a medication targeting HER-2 in breast cancer treatment, was found to elevate mitochondrial ROS levels in rat cardiomyocytes while reducing GPX4 expression, thereby leading to ferroptosis." (PMID 39867656, 2024). "Targeting the previously unappreciated RUNX1-IT1/IGF2BP1/GPX4 regulatory axis may be a promising treatment for breast cancer patients." (PMID 38550378, 2024). "The derivative of the natural product chamomile lactone, DMOCPTL, can induce ferroptosis in breast cancer cells by directly binding to GPX4 protein, leading to tumor growth inhibition in mice and extending mouse lifespan significantly without observable toxicity." (PMID 39664391, 2024). "Moreover, it also demonstrated suppressive action on the PI3K/AKT/mTOR pathway and an antioxidant effect mediated through the upregulation of the antioxidant enzymes, SOD and GPX4 against an experimentally induced mammary carcinoma animal model." (PMID 39519654, 2024). "RGP promotes ferroptosis of lung and breast cancer cells by downregulating GPX4 expression." (PMID 39021832, 2024).